TLR4 (toll like receptor 4)
Diseases named in the same sentence as TLR4 in open-access papers (continued):
Sharing a sentence is not in itself a finding about the gene and the disease.
infection (continued). "Ad-SOCS2 infection alleviated STZ-induced renal injury and pathological changes and inhibited STZ-induced IL-6, IL-1β and MCP-1 generation and activation of the TLR4/NF-κB pathway in DN rats." (PMID 29207635, 2017). "Together, these results for the first time demonstrated differential TLR4 signaling in course of A. hydrophila pathogenesis wherein MyD88 pathway is involved at the early stages and TRIF pathway at later stages of infection." (PMID 29142761, 2017). "The predominant response of buffaloes to infection was mediated by certain pathways, such as MHC antigen processing and presentation, Toll-like receptor 4 (TLR4), transforming growth factor beta (TGF-β), and the cytochrome P450." (PMID 28143561, 2017). "In this context pattern recognition receptors like TLR2, TLR4 and NLRP3 but also oxidative stress and antioxidant responses that are also responsible for infection defense play an important role." (PMID 30402600, 2017). "In our study, expression of TLR4, TLR5, NLRC4, caspase-4, and matured IL-18 and IL-1β cytokines was induced in hCFs after infection with P. aeruginosa wild-type strains." (PMID 28469996, 2017). "Given that in the primary infection the increase in ASM mass was TLR4 dependent, we next sought to investigate if TLR4 in later life contributed to the development goblet cell hyperplasia, ASM mass and AHR." (PMID 28099113, 2017). "Many markers that are supposed to be involved in the activation of CD14, TLR4, and TLR2 on monocytes and macrophages during infections have also been studied." (PMID 27252945, 2016). "In the brain isolated from mice at 2 days post-infection (dpi) with Acanthamoeba strains Ac55 and Ac43, mRNAs for TLR2 and TLR4 were significantly more strongly expressed in comparison with the uninfected mice." (PMID 27511368, 2016). "For instance, IBV 2575 AT infection activated multiple PRR genes, including IFIH1, TLR1LA, TLR2-2, TLR3, TLR4, TLR7, and TLR15." (PMID 27876864, 2016). "Above study indicated that TLRs were differentially distributed among various CNS cell types upon infection, e.g., TLR2 was localized to nervous tissue cells, particularly astrocytes, but TLR4 was localized to microglia and neurons." (PMID 27511368, 2016). "The innate cellular response to the initial stages of infection is mediated by Toll like receptor (TLR2, TLR4, TLR9) signaling, these receptors have been shown to recognize the surface proteins of CMV and RSV." (PMID 27340772, 2016). "We report here for the first time that G1-4A, a polysaccharide immunomodulator and TLR4 agonist from Tinospora cordifolia, inhibits the survival of MTB in macrophages as well as in murine infection model." (PMID 27148868, 2016). "Three days after H9N2 infection, the expression of CD14, TLR4, ERK and JNK protein in the lung tissue was measured." (PMID 27793190, 2016). "We have now analyzed the role of TLR2, TLR4 and TLR9 in the control of B. microti infection and found that in vivo TLR2 and TLR4 cooperate to eliminate this pathogen, while TLR9 is dispensable to control the infection." (PMID 28119856, 2016). "After ex vivo infection with L. braziliensis, the expression of TLR2 and TLR4 increased significantly in monocytes isolated from CL patients (32 ± 26 versus 90 ± 64, and 14 ± 7 versus 55 ± 32, respectively), p<0.001." (PMID 26840253, 2016). "Mouse models of infection have shown that UPEC can invade bladder epithelial cells in a type 1 pilus-dependent mechanism, avoid a TLR4-mediated exocytic process, and escape into the host cell cytoplasm." (PMID 27073089, 2016). "We investigated whether infection of THP-1 macrophages by BCG-OtsB2 was associated with changes in cell-surface expression of a number of immune-related receptors including a number of receptors such as TLR2, TLR4, Mincle, Dectin-1 and CD-14 that have been implicated in phagocytosis of mycobacteria." (PMID 27867377, 2016).
infection (continued). "Upon infection with Ct, the bacterial LPS is bound by LPS binding protein (LBP) and transferred to a receptor complex consisting of CD14, TLR4, and the adapter molecule MD2." (PMID 27559544, 2016). "Several studies have shown that infection with P. acnes involves an interaction with TLR2 and TLR4 on keratinocytes." (PMID 26197393, 2015). "It indicated that TLR4 and MYD88 were significantly increased in H1N1-SS2 infection group, which play important roles in TLR signaling." (PMID 25906258, 2015). "The expression of IE1–72, TLR2, TLR4, NF-κB and TNF-α mRNA was quantified at different time points prior to and following infection." (PMID 25435993, 2015). "However, lack of TLR4 could result in endothelial cells not being able to sense pathogens, and render tissue/organs immune-suppressed and thereby susceptible to infection with Gram-negative bacteria." (PMID 24690886, 2014). "Following infection by pathogens and in inflamed tissues, increased expression of TLR2 and TLR4 has been reported." (PMID 25161655, 2014). "TLR4 is capable of inducing type I interferon production via either MYD88 or the alternative adapter TRIF, but infection of Tlr2/Tlr4 double knock-out cells induced antiviral gene expression, ruling out a role for TLR4 as well." (PMID 24505488, 2014). "Higher immunoreactivity of TLR4 observed in decidual cells compared to interstitial trophoblasts suggested maternally derived cells as the main protectors against Gram-negative bacteria and other harmful signals from severe inflammation associated with or without infection." (PMID 23161283, 2013). "The TLR3 levels peaked at 9 h after hMPV infection, and the levels of TLR4 and TLR7-9 peaked at 12 h after infection, then started to decline." (PMID 24039959, 2013). "The mRNA expression of TLR4 is significantly upregulated, whereas the expression of MUC2 is significantly downregulated upon infection." (PMID 24367242, 2013). "Level of the Th1 regulatory cytokine IFN-γ was also significantly reduced in TLR4−/− mice on various days p.i, in particular on day 5, which corresponds to peak levels of IFN-γ production in response to hMPV infection." (PMID 24205331, 2013). "Remarkably, TLR4 seemed to protect against epithelial barrier disruption, as indicated by increased protein levels in BAL fluid of tlr4−/− mice early after infection." (PMID 24342460, 2013). "Consistent with previous reports, B. thailandensis upregulated expression of TLR1 and TLR2 by two h post-infection, and increases in TLR1, TLR2, TLR3, TLR4, and TLR5 mRNA expression were observed by eight h post-infection." (PMID 23675544, 2013). "In conclusion, we demonstrate that TLR-4 engagement in immature DC significantly up-regulates the intrinsic antiviral activity of BST-2/tetherin, during cis-infection of CD4+ T cells across the DC/T cell virological synapse." (PMID 23311681, 2013). "After confirming overexpression of MyD88 and Mal in HCE cells, we co-transfected the NF-kB reporter plasmid together with TLR4/MD2, Mal/MyD88 and measured luciferase activity at 4 h after HSV-2 infection or mock-infection." (PMID 24278275, 2013). "Brucella stimulates both TLR2 and TLR4 and the TLR adaptor MyD88 appears to be essential for controlling infection in vivo." (PMID 24339776, 2013). "Three of ten human toll-like receptors (TLRs), TLR2, TLR4, and TLR9, have been reported to play roles in the recognition of T. gondii, course of infections with this parasite, and also in pregnancy progression and disorders." (PMID 23161283, 2013). "Subsequent LVS infection, Acai PS enhanced surface expression of CD11b, CD40, CD80, CD86, TLR2, and MHC class II in a dose-dependent fashion, while TLR4 expression was downregulated in both mock- and LVS- infected macrophages." (PMID 22438809, 2012).
infection (continued). "The reactivity of peritoneal macrophages from the mice infected with lethal strain P. y 17XL or non-lethal strain P. y 17XNL were enhanced to pRBC lysate, and TLR2, TLR4, and TLR9 agonists at one, three and five days post-infection." (PMID 22463100, 2012). "Together these results indicate that TLR4, as previously shown for TLR2 and TLR9, also contributes to resistance during the acute phase of infection in B6 mice." (PMID 22496959, 2012). "Collectively, to date, the analysis of different mice strains lacking one or multiple TLR pathways demonstrated that TLR2, TLR4, TLR7, and TLR9 play a role in the resistance to infection with T. cruzi, with a degree of redundancy between them." (PMID 22496959, 2012). "Significantly fewer mice succumbed to infection from the TLR2−/− group and symptoms of disease were also reduced in TLR2−/− mice compared to both wild type and TLR4−/− mice, serum levels of IL-6 were significantly reduced in TLR2−/− mice." (PMID 23061052, 2012). "TLR4 expression level (ΔCt expressed as mean ± 1 SD; n = 10) in PMNs prior to BHV-1 infection (Day 0) were 0.40 ± 0.62 (WMS) and 0.15 ± 0.85 (PA)." (PMID 22435642, 2012). "The infection of human THP1-derived macrophages by L. donovani in vitro suppresses TLR2 and TLR4-stimulated IL-12 release, with an increase in IL-10 production, through parasite-dependent contact." (PMID 22523644, 2012). "This is in agreement with some previous studies that had also reported inhibition of infection of VSV-G-pseudotyped HIV-1 virions by TLR3 and TLR4 agonists (poly(I∶C) and LPS, respectively) in primary human myeloid cells." (PMID 23028330, 2012). "We demonstrate that CHPV infection regulates the TLR4 during infection in RAW cells and TLR4 and NO involved in disease pathogenesis in mice." (PMID 22642811, 2012). "The resistance to infection with T. cruzi is known to depend on appropriate MyD88 signaling after stimulation of TLR2 and TLR9, and TLR4." (PMID 22348160, 2012). "At high multiplicities of infection (10 MOI), RAW cells up- regulated cell surface expression of TLR4 and secreted significant amounts of TNF-α, MCP-1, IL-10 and IL-12 and NO." (PMID 22642811, 2012). "Infection with Chlamydia pneumoniae promotes atherosclerotic lesion development via the formation of foam cells in mice; knockout of TLR2, TLR4, MyD88, TRIF, or IRF3 all reduced this process." (PMID 23730203, 2012). "Like the response of macrophages to pRBC lysate, macrophages from P. yoelii 17XL- or 17XNL-infected mice responded to TLR2, TLR4, and TLR9 agonists much more strongly than macrophages from nRBCs-injected mice at one and there days post-infection." (PMID 22463100, 2012). "TLR4 expression was reduced after GBS stimulation (3.4-fold after 4 hours, 2.9-fold after 8 hours, and 11-fold after 24 hours of infection)." (PMID 21437210, 2011). "Overall, the fact that expression of IFN-β was unimpaired in TLR2, TLR4 and TLR9 KO BMDM during infection strongly indicated that Brucella- or its DNA-induced IFN-β expression occurs mostly independent of TLRs." (PMID 21829705, 2011). "At day 12 following peroral infection with C. jejuni ATCC 43431, significant histopathological changes in colon sections of wildtype (WT) mice such as loss of goblet cells, crypt elongation, and immune cell infiltration could be observed which were less pronounced in infected TLR4-deficient mice." (PMID 21698299, 2011). "When comparing PBMCs obtained from children undergoing infection from each ethnic group, the IFN-γ/IL-10 ratio was significantly higher in Fulani than in Dogon upon stimulation with TLR4 and TLR9 ligands (p = 0.002 and p = 0.0051; respectively)." (PMID 21483827, 2011). "Analysis of MyD88−/−, TRIF−/−, TLR4−/−, and TLR9−/− mice revealed that TLR4- and TLR9-signaling was essential for immunopathology following C. jejuni-infection." (PMID 21698299, 2011).
infection (continued). "One study proved that the expression levels of TLR-2, TLR-4, TLR-9 and TLR-11 were significantly raised in mouse IECs following infection with Toxoplasma gondii on day 8 post-infection." (PMID 21943110, 2011). "This is consistent with the results obtained in our study where the enhancement of TLR4 was accompanied of increased number of TLR2 (+) cells previous and post infection." (PMID 21813005, 2011). "Upon infection of mice with E. coli or treatment with LPS, the number of CD4+ and CD8α+ DCs was markedly reduced 48 hours later, a result of TLR4-TRIF signaling induced apoptosis." (PMID 21124820, 2010). "Regardless of the mechanism, maturation of DCs with ligands for TLRs such as TLR4 and TLR2/TLR1 increases DC-mediated HIV-1 capture and trans-infection of T cells." (PMID 20617179, 2010). "Tlr4−/− and Myd88−/− mice developed significant bacteriuria (≥105 CFU/ml of urine) six hours after infection with CFT073 or ΔTcpC and bacteria persisted in urine until the experimental end point." (PMID 20886104, 2010). "The genomic regions carrying the candidate genes TLR4 and SLC11A1, the Major Histocompatibility Complex (MHC) and the QTL SAL1, identified using several infection models, are interesting candidates for more in-depth studies." (PMID 20429884, 2010). "The role of individual receptors such as TLR2, TLR4, and TLR9 in MyD88 activation varies depending on the fungus and the site of infection." (PMID 17676994, 2007). "To help resolve this valid scientific concern we did a study in which we compared infection with Leptospira interrogans serovar Copenhageni Fiocruz in mice expressing fully competent tlr4 (C3H-HeN, C57BL6) versus tlr4 hyporesponsive mice (C3H-HeJ) over a period of two weeks." (PMID 39975062, 2025). "tlr4 mutant mice infected with inoculums lower than 105 CFU also gave less optimal results; the 104 inoculum resulted in slightly earlier clearance, and the 103 inoculum resulted in inconsistent infection." (PMID 40817088, 2025). "At the higher inoculum, WT and tlr4 mutant mice exhibited significantly increased levels of IL-1α, IFN-γ, TNF-α, MCP-1, IL-1β, IL-6, and IL-17A early during infection relative to the lower inoculum while levels dissipated by 7 dpi, consistent with bacterial clearance." (PMID 40817088, 2025). "Moreover, LPS molecules can interact with host immune receptors, such as Toll-like receptor 4 (TLR4), initiating inflammatory responses that lead to cytokine production and other immune mediators essential for host defense against infection." (PMID 41155151, 2025). "The results revealed distinct temporal expression profiles of Toll-like receptors (TLRs), showing that TLR2, TLR4, TLR7 and TLR10 were significantly upregulated in a parabolic pattern, with TLR2 and TLR10 peaking at 36 h while TLR4 and TLR7 reached maximum expression at 24 h post-infection." (PMID 41305370, 2025). "Because OP18 does not bind to the TLR4 dimerization interface, it neither antagonizes TLR4 nor impairs downstream signaling crucial for host defense against infection." (PMID 40421030, 2025). "Since HEK-293 cells express neither TLR2 nor TLR4, these data suggest that the improved release of IL-8 by Caco-2 in response to the infection with M90T ΔvirK and ΔybjXΔvirK derivatives likely relies on the activation of the TLR signaling pathways." (PMID 41144768, 2025). "While the roles of a few isolated receptors (including TLR2, TLR4, and TLR9) have been explored, the relative contributions of these and other TLRs to the host’s overall ability to control infection, as well as the potential interactions between these receptors, remain poorly understood." (PMID 40248691, 2025). "We found that TLR2, TLR4, TLR9, and the TLR3/4 adaptor molecule TRIF are dispensable for inducing host resistance against the subsequent infection, as observed by reduced bacterial loads in the lung of mice that were first infected with Lp thyA L. pneumophila compared to mock." (PMID 40558085, 2025).
infection (continued). "Collectively, these results indicate that both TLR4 and SLAMF1 are required for the early induction of TNF mRNA by HMPV in human MDMs, while only SLAMF1 contributes to HMPV-mediated IFNB1 expression at later stages of infection." (PMID 41346628, 2025). "Here, silencing TLR4 or SLAMF1 in MDMs reduced HMPV-induced p38 MAPK activation at early time points, indicating that HMPV triggers signaling downstream of both receptors early during infection in MDMs." (PMID 41346628, 2025). "There are also shared infection-related pathways, which may be indicative of Toll-like receptor 2 (TLR2) and TLR4 activation." (PMID 40059827, 2025). "Our data supports the hypothesis that genetic variations in TLR-4 may influence immune responses to HPV, potentially affecting viral persistence and infection outcomes." (PMID 41374999, 2025). "Furthermore, the increased expression of TLR4 in the lungs of DDX5+/- mice upon infection with P. multocida and of TLR2 upon infection with S. aureus and M. pneumoniae was confirmed by immunohistochemistry staining." (PMID 38182816, 2024). "Nevertheless, we demonstrated that the presence of TLR4 is very relevant to this process as the infection of shTLR4 cells with the co-culture failed to induce any increment in IL-6 expression compared to the non-infected control." (PMID 38612423, 2024). "TLR4 mutant C3H/HeJ mice can control Mb BCG infection as well as C3H/HeOUJ control mice, with efficient macrophage recruitment and activation, but they have arrested body weight and develop chronic exacerbated inflammation at later stages of infection." (PMID 38892353, 2024). "Cytokine production in response to infection with Gram-negative organisms is determined by the interaction of LPS with host TLR4/MD2 receptors." (PMID 38771050, 2024). "Moreover, several publications have demonstrated that CD14, TLR4, and MD2 gene expression decreases when the inflammatory response to LPS infection is inhibited." (PMID 38785798, 2024). "Previous studies show that neutrophils phagocytose both opsonized and non-opsonized STm, and that infection with wild-type-LPS-expressing Salmonella results in the generation of reactive oxygen species (ROS) in TLR4-decorated, Salmonella-containing vacuoles." (PMID 38398044, 2024). "However, at the 8th week post-infection, PD-1 (P = 0.0420), PD-L1 (P = 0.0406), TCR (P = 0.0423), Bcl-2 (P = 0.0178), Caspase-3 (P = 0.0349) and TLR4 (P = 0.0449) were upregulated in undernutrition 75% + infection group." (PMID 38185681, 2024). "In mice, TLR-4 has also been involved in the reactivation of cytomegalovirus, which has been previously intra-peritoneally injected (as a non-sterile infection/inflammatory model), from latency after LPS stimulation." (PMID 37508529, 2023). "Similarly, to study the effect of TLR4 inhibition on the translation of E2 protein, the CHIKV-infected RAW264.7 cells were subjected to post-infection incubation (0 hpi) with TAK-242 (1μM) or DMSO." (PMID 37153546, 2023). "Further, while previously thought to be incapable of infecting lymphocytes, more recent evidence indicates that EBOV is infectious to T cells – though this infection is not productive and induces host cell autophagy, mediated by GP and TLR-4/ER-stress." (PMID 38035334, 2023). "Thus, the activation of TLR2 and TLR4 on other cells promotes platelet production, while the activation of TLR2 and TLR4 on platelets can regulate their functions, such as anti-infection, adhesion, and aggregation." (PMID 36674552, 2023). "Additionally, in human biliary epithelial cells, infections in vitro result in recruitment of TLR2 and TLR4 and are mediated by the activation of NF-κB activation, and result in the production of human β-defensin." (PMID 37325809, 2023). "LPS treatment is used to stimulate sterile inflammation in culture by acting on Toll Like Receptor 4 (TLR4), a cellular membrane sensor of damage and infection that also triggers the caspase-11 non-canonical inflammasome." (PMID 37051469, 2023).